ORC6 (origin recognition complex subunit 6)
Diseases named in the same sentence as ORC6 in open-access papers (continued):
Sharing a sentence is not in itself a finding about the gene and the disease.
tumor (15 papers, 2007 to 2025). "Dysregulation of ORC6 has been associated with aggressive tumor behavior and poor patient outcomes, positioning it as a potential biomarker and oncotarget." (PMID 38971772, 2024). "Through ROC curves, we also found that ORC6 was a highly accurate diagnostic marker for most tumor types." (PMID 37901236, 2023). "Notably, GSEA revealed a strong association between ORC6 expression and the cytokine-cytokine receptor interaction pathway, and our GSEA further highlights the close association between ORC6 and immune-related pathways in multiple tumor types." (PMID 37901236, 2023). "ORC6 may be considered a diagnostic biomarker and its expression levels tended to increase with increasing tumor stage and grade." (PMID 35711825, 2022). "Additionally, the biological function of ORC6 may be linked to RNA modifications, DNA methylation, and the tumor immune microenvironment." (PMID 37901236, 2023). "Combining all 20 sets of tissue data, the collective analysis demonstrated a significant upregulation in ORC6 protein expression in NSCLC tumor tissues." (PMID 39349930, 2024). "Examination of tissue lysates verified a substantial increase in ORC6 mRNA expression within NSCLC tumor tissues compared to normal lung epithelial tissues." (PMID 39349930, 2024). "ORC6 expression levels were significantly elevated in LUAD tissues (“Tumor”) compared to normal lung tissues (“Normal”)." (PMID 39349930, 2024). "To investigate the effect of ORC6 on tumor prognosis, we plotted survival curves and assessed OS using the Kaplan–Meier method." (PMID 37901236, 2023). "Single-cell functional analysis also indicated that ORC6 expression was positively correlated with the cell cycle and proliferation of tumor cells." (PMID 37901236, 2023). "Unpaired Wilcoxon rank sum and signed rank tests were used to analyze the differences in the expression of ORC6 in normal tissues and corresponding tumor tissues." (PMID 37901236, 2023). "This study underscores the correlation between high ORC6 expression and the tumor immunosuppressive environment." (PMID 37901236, 2023). "We conducted a comparative analysis of ORC6 expression in tumor vs. normal tissues by merging the TCGA and GTEx databases." (PMID 37901236, 2023). "Thirdly, ORC6 was identified to influence the tumor immune microenvironment by adjusting the immune cell infiltration." (PMID 36978046, 2023). "Previous studies have demonstrated that ORC6 is involved in a range of biological events during tumor progression." (PMID 36978046, 2023). "After performing a chi-square test analysis, we discovered a significant correlation between ORC6 expression and tumor histological grade, alpha-fetoprotein (AFP) content, and vascular invasion in LIHC." (PMID 37901236, 2023). "Nevertheless, the mechanisms by which ORC6 regulates the tumor immune microenvironment and tumor progression need to be further elucidated in the future." (PMID 37901236, 2023). "The present study observed the mRNA expression level of ORC6 was overexpressed in 72 ccRCC tumor tissues compared with in normal tissues." (PMID 35711825, 2022). "All in all, in the present work, we report the expression, biological functions, and regulatory mechanism of the tumor suppressor miR-1-3p and the tumor-promoting factor ORC6 in HCC." (PMID 34395415, 2021). "Our data suggest that ORC6 is a novel tumor-promoting factor in HCC, and the downregulation of miR-1-3p contributes to its dysregulation in HCC." (PMID 34395415, 2021). "We also demonstrate that in HCC, miR-1-3p is a tumor suppressor, and ORC6 can facilitate cancer progression." (PMID 34395415, 2021). "Additionally, the protein expression of ORC6 exhibited an upregulation in NSCLC tumor tissues from four selected patients (“T1” to “T4”)." (PMID 39349930, 2024). "Interestingly, ORC6 expression is also significantly elevated in LUSC tissues (“Tumor”), when compared to that in normal lung tissues (“Normal”)." (PMID 39349930, 2024).
tumor (continued). "High expression of ORC6 may be used as a biomarker to predict the poor prognosis of most tumor patients." (PMID 37901236, 2023). "Finally, we identified and subsequently validated in the TGCA, the prognostic potential of ORC6, the sixth subunit of a DNA-binding complex, shown to be dysregulated in a number of neoplasms." (PMID 37965470, 2023). "Therefore, we analyzed differences in the DNA promoter methylation levels of ORC6 between tumor and normal tissues using UALCAN." (PMID 37901236, 2023). "Furthermore, we identified a positive correlation between ORC6 expression and m1A-, m5C-, and m6A-related genes in almost all of the analyzed tumor types." (PMID 37901236, 2023). "The results of this study suggest that elevated ORC6 levels may serve as a valuable prognostic marker for adverse outcomes in most tumor types." (PMID 37901236, 2023). "The high expression of ORC6 may be involved in the regulation of the tumor immunosuppressive environment, and it is expected to become a molecular target for inhibiting tumor progression." (PMID 37901236, 2023). "Here, we found an inverse correlation between the expression level of ORC6 and the abundance of immune cells widely believed to contribute to the suppression of tumor infiltration, including Tem CD8 cells, Th1 cells, NK cells, pDCs, iDCs, eosinophils, and monocytes." (PMID 37901236, 2023). "The atypical correlation between ORC6 overexpression and prognosis in OV may be attributed to the fact that ORC6 is under-expressed exists in the higher stage of OV tumor tissues compared to the lower stage." (PMID 36978046, 2023). "High expression of ORC6 correlates with an immunosuppressive state in the tumor microenvironment." (PMID 37901236, 2023). "Additionally, ORC6 was involved in the cell cycle pathway, DNA replication, and mismatch repair pathways in most tumor types." (PMID 36978046, 2023). "In hepatocellular carcinoma, it has been demonstrated that ORC6 may promote the tumor proliferation, migration, and invasion." (PMID 36978046, 2023). "RT-qPCR assay indicated that ORC6's mRNA expression in ccRCC cells (786-O, Caki-1, ACHN, A-498, OSRC-2) was significantly higher than HK-2 cells, and that compared with normal tissues, ORC6's mRNA expression in ccRCC tumor tissues was also higher (13 cases of 15 cases were upregulated)." (PMID 35711825, 2022). "Furthermore, higher expression levels of ORC6 were associated with higher pathological grade, TNM stage, higher tumor T stage, distant metastasis, lymph node metastasis in ccRCC." (PMID 35711825, 2022). "Therefore, targeting ORC6 could potentially offer a precise method for identifying Tprolif and malignant cells, leading to novel avenues for tumor immunotherapy." (PMID 37901236, 2023). "Furthermore, cell cycle-related proteins, including cyclin D1, CDKs, ORC6 and MCMs, were downregulated in the xenograft tumour tissues after treatment with T-96 compared with controls, and these trends were largely consistent with the previous experimental results." (PMID 30305611, 2018). "Following this, we conducted Cox regression analysis to assess the correlation between ORC6 expression and several survival outcomes, including OS, DSS, DFI, and PFI, for each tumor type." (PMID 37901236, 2023). "This might elucidate the favorable correlation between ORC6 and Treg infiltration abundance in BRCA, KIRC, MESO, and THCA, whereas an inverse correlation exists in the majority of other tumor types." (PMID 37901236, 2023). "Interestingly, in most tumor types, immunosuppression-related genes, especially TGFBR1 and PD-L1 (CD274), exhibited a specific correlation with the ORC6 expression." (PMID 36978046, 2023). "Furthermore, in most tumor types, immunosuppression-related genes, especially TGFBR1 and PD-L1 (CD274), exhibited a specific correlation with the expression of ORC6." (PMID 36978046, 2023).
tumor (continued). "Tissues of normal bladder, breast, cervix, colon, oral tissue, kidney, cerebral cortex, liver, lung, ovary, pancreas, prostate, rectum, stomach, testis, thyroid, and endometrium had negative or moderate ORC6 IHC staining, while the corresponding tumor tissues had moderate or strong staining." (PMID 36978046, 2023). "Interestingly, five genes (CDC45, KIF13B, ORC6, SHCBP1,and CAPN8) were not present in previously reported molecular tumor grading signatures." (PMID 26474389, 2015). "The lack of correlation between high ORC6 expression and poor survival in male LUAD patients may stem from various factors such as biological differences, tumor microenvironment variations, treatment responses, or genetic and hormonal influences specific to males." (PMID 39349930, 2024).
adenocarcinoma (1 paper, 2020). A common cancer characterized by the presence of malignant glandular cells. "We also found that SOX4, ORC6, and CCDC34 were more highly expressed in adenocarcinoma tissue than in normal gastric tissue using Western blot (WB) assays and immunohistochemistry (IHC)." (PMID 33188157, 2020). "Moreover, SOX4, ORC6, and CCDC34 are located mainly in the nucleus of adenocarcinoma tissues." (PMID 33188157, 2020).
ORC6 also shares sentences with these, for which no sentence is quoted: Gorlin syndrome (3 papers); primordial dwarfism (3); non-small cell lung carcinoma (2); rectal cancer (2); testis cancer (2); cervical cancer (1); dwarfism (1); gastric cancer (1); HIV-1 infection (1); intrahepatic cholangiocarcinoma (1); liver cancer (1); microcephaly (1); nasopharyngeal carcinoma (1); ovarian carcinoma (1); renal carcinoma (1); thyroid cancer (1); Werner syndrome (1).